BMI1 (BMI1 proto-oncogene, polycomb ring finger)
Diseases named in the same sentence as BMI1 in open-access papers (continued):
Sharing a sentence is not in itself a finding about the gene and the disease.
ovarian carcinoma (continued). "The tumorigenic activity of BMI1 also appeared to be independent of ARF signaling in human ovarian cancer cells, where genetic or pharmacological BMI1 inhibition impaired clonal growth without affecting expression of the CDKN2A locus or ARF protein stability." (PMID 33445626, 2021). "In this study, we set out to analyze the immunohistochemical (IHC) BMI-1 expression in two different groups: endometriosis-related ovarian carcinoma (EOC) and non-endometriotic ovarian carcinoma (NEOC), aiming to identify the differences in its tissue profile." (PMID 34199929, 2021). "BMI1 and EZH2, which are members of the PRC1 and PRC2 complexes respectively, and therefore partners in the action of lncRNAs in the control of gene expression, have been shown to be deregulated in ovarian cancer." (PMID 26992233, 2016). "Interestingly, EMT-related Snail and Slug transcription factors have been shown to induce a self-renewal program in ovarian cancer by upregulation of Nanog, Oct4, HDAC1&3 and Bmi1." (PMID 22276221, 2012). "Intensive expression of Bmi-1 was detected in none of the normal ovaries, 3% cystadenomas, 10% borderline tumors, and 37% ovarian carcinomas, respectively." (PMID 20377880, 2010). "To date, however, the status of Bmi-1 expression and its clinical/prognostic relevance in ovarian cancer have not been fully elucidated." (PMID 20377880, 2010). "Consistent with previous reports of other types of human cancer, in this study, we found that intensive expression of Bmi-1 in ovarian carcinoma was a predictor of short overall survival, independent of stage and grade." (PMID 20377880, 2010). "However, inhibition of AKT by specific inhibitors (AKTi) reduced but did not eliminate the characteristic phospho-bands of BMI1 in ovarian cancer cells, CP20 and OV90." (PMID 28270146, 2017). "Also, in the present study, we did not observe a significant correlation between Bmi-1 expression and either p16Ink4a or p14ARF expression in ovarian carcinoma cohorts." (PMID 20377880, 2010).
lung cancer (57 papers, 2008 to 2025). A malignant neoplasm involving the lung. "Although clinical studies confirmed the association of BMI1 with a poor survival in lung cancer patients, how BMI1 drives the tumorigenesis in lung cancer remains elusive." (PMID 35794816, 2022). "In lung cancer, the common stem-cell-associated markers include Bmi1, CD133, CD44, Sox2, OCT4 and so on." (PMID 23683495, 2013). "Loss of Bmi1 has been previously shown to inhibit the tumor development in multiple mouse models, such as K-Ras induced lung cancer or hedgehog pathway-driven medulloblastoma." (PMID 23029524, 2012). "In previous studies, we showed that targeting BMI-1 with the preclinical compound PTC-209 (PTC Therapeutics) resulted in significant in vivo antitumor activity in xenograft lung cancer models characterized by low C/EBPα expression." (PMID 38546390, 2024). "The cancer stem-cell-related protein BMI1 is overexpressed in lung cancer and is important for maintaining this phenotype and resistance to pemetrexed." (PMID 36982239, 2023). "The current study focused on the role of stemness factor BMI1 in lung cancer, and its crosstalk with EGFR through JNK‐mediated protein stability regulations." (PMID 35794816, 2022). "Silencing of CBX4 inhibited cell growth and metastasis in lung cancer by regulating the BMI-1 pathway." (PMID 36292141, 2022). "In lung cancer patient samples, high level of BMI1 is correlated with poor survival, and the expression of BMI1 is positively correlated with MCL1." (PMID 35794816, 2022). "It has been found that the expression of miR-145 was negatively correlated with high expression of BMI1 in CSCs derived from SPC-A1 lung cancer cells." (PMID 36499676, 2022). "Since EGFR regulates multiple oncogenic pathways in lung cancer, we tried to clarify through which pathway it positively regulates BMI1." (PMID 35794816, 2022). "In a study of lung cancer, BMI1 overexpression was correlated with large tumor size, poor differentiation, distant metastasis, and worse survival in non-small-cell lung cancer (NSCLC)." (PMID 34442383, 2021). "Taken together, these results suggest that the expression of BMI‐1 is regulated by CBX4, and that BMI‐1 overexpression can effectively reverse the function caused by knocking down of CBX4 in lung cancer cells." (PMID 31724308, 2020). "Our study provides a novel insight into the proliferation and migration of CBX4 and suggests that knockdown of CBX4 reduces the abilities of proliferation and metastasis via BMI‐1 in lung cancer." (PMID 31724308, 2020). "In lung cancer, CBX4 regulated the expression of BMI-1 to promote proliferation and metastasis in lung cancer cells, and its expression was positively correlated with tumor size." (PMID 33344640, 2020). "In this study, we firstly demonstrated that CBX4 regulated proliferation and migration by regulating the expression of BMI‐1 in lung cancer cells." (PMID 31724308, 2020). "The results demonstrated that overexpression of miR-128 inhibits MUC1-C and BMI-1 expression in paclitaxel-resistant lung cancer cells, thereby suppressing paclitaxel-resistant lung cancer." (PMID 29299167, 2017). "Restoration of AMPK phosphorylation in lung cancer cells leads to down-regulation of the transcription regulator Bmi-1, which has been shown to promote EMT and its expression is associated with cell progression." (PMID 28423657, 2017). "On the other hand, in lung cancer tissue the BMI1 protein expression seem to be more variable and dependent on type of anti-BMI1 antibodies used for detection (HPA030472 antibody is much more sensitive as CAB011120 antibody)." (PMID 28445986, 2017). "The prognostic effect of B-cell-specific Moloney leukemia virus insertion site 1 (Bmi-1) in patients with nonsmall cell lung cancer (NSCLC) remains controversial." (PMID 28658153, 2017).
lung cancer (continued). "In lung cancer, several studies confirmed aberrant expression of BMI1 in NSCLC tumors, but, to the best of our knowledge, correlation between Bmi1 and CSCs has not been demonstrated until now." (PMID 26770215, 2016). "Nanog therefore possessed high diagnostic value, however, CD44, Bmi1 and CD133 showed poor diagnostic value in lung cancer." (PMID 23683495, 2013). "Vrzalikova and colleagues also believed that the expression of Bmi1 in surgically resected lung cancer tissues is a prognostic marker in lung cancer." (PMID 23683495, 2013). "In HeLa cervical cancer cells an LD50VM26 of 0.3 μM was measured with Bmi1 siRNA compared to 3.5 μM with a control siRNA, and in A549 lung cancer cells an LD50VM26 of 1.1 μM was measured with Bmi1 siRNA compared to 7.4 μM with the control siRNA." (PMID 19956605, 2009). "CBX4 promotes proliferation through affecting BMI-1 expression in lung cancer cells." (PMID 36999051, 2023). "For example, CBX4 was found to be highly expressed in lung cancer and could promote tumor cell proliferation and metastasis by regulating BMI-1 expression." (PMID 33464142, 2021). "Further analysis of data from the GEO database also revealed that USP4 expression was downregulated in different head and neck, breast, and lung cancer cells following enhancement of stemness by sphere formation, Bmi1 and Snail overexpression, or chemotherapeutic treatments." (PMID 31936290, 2020). "Additionally, CBX4 promotes proliferation and metastasis via regulating the expression of BMI‐1 which is a significant regulator of proliferation and migration in lung cancer cells." (PMID 31724308, 2020). "Notably, CBX4 knockdown inhibited the abilities of proliferation and migration in lung cancer cells, thereby decreasing the expression of BMI‐1." (PMID 31724308, 2020). "It is evident that BMI1 gene dosage is a critical checkpoint that lung cells must overcome to achieve transformation, but nevertheless, mechanisms controlling BMI1 regulation in lung cancer and other epithelial tumors remain un-identified." (PMID 28445986, 2017). "MUC1 and BMI1 are direct targets of miR-128 in paclitaxel-resistant lung cancer cells." (PMID 29299167, 2017). "Large scale genomic projects, such is The Cancer Genome Atlas (TCGA) could provide additional BMI1 expression data in lung cancer patients." (PMID 28445986, 2017). "The purpose of this study is to investigate the differential expression and clinical significance of seven stem-cell-associated markers (Bmi1, CD133, CD44, Sox2, Nanog, OCT4 and Msi2) in lung cancer, providing new targets for the diagnosis and treatment of lung cancer." (PMID 23683495, 2013). "Our results may be explained by the fact that TAM-derived SPP1 induces BMI1 in lung cancer cells." (PMID 36139536, 2022). "An alternative method to confirm BMI1 expression in lung cancer tissue could be IHC." (PMID 28445986, 2017). "We found the positive expression rates of Nanog and Bmi1 mRNA was inversely correlated to differentiation of lung cancer, indicating these two markers may be useful to predict tumor progression and poor prognosis in lung cancer." (PMID 23683495, 2013). "Hence, Bmi1, CD44 and CD133 are poor diagnostic markers for lung cancer." (PMID 23683495, 2013).
lung cancer (continued). "Bmi1 was diffusely expressed in bronchial epithelium cells, alveolar epithelium cells, lung interstitial cells and some inflammatory cells of all non-malignant lung tissues, and was diffusely expressed in 47 cases of lung cancer and focally expressed in 1 case of Ad and 1 case of SCLC." (PMID 23683495, 2013). "We further analyzed the effects of SET KD on Bmi-1 protein in MIA PaCa-2 (pancreatic cancer), A549 (lung cancer), HT-29 (colon cancer), and SH-SY5Y (neuroblastoma)." (PMID 38141761, 2024). "Hub genes including LRRK2, BMI1, MNDA (myeloid cell nuclear differentiation antigen), OTX1, FFAR2, and PITX1 play a significant role in lung cancer progression." (PMID 38137330, 2023). "Targeting BMI1/MCL1 thus provides a new and promising therapeutic approach for the treatment of lung cancer." (PMID 35794816, 2022). "In this study, we found that in non‐small cell lung cancer (NSCLC), BMI1 and MCL1 play crucial roles of cancer stemness including invasion, chemo‐resistance and tumour initiation." (PMID 35794816, 2022). "Here, we found that deguelin inhibited the growth of non‐small cell lung cancer (NSCLC) cells both in vitro and in vivo by downregulation of Bmi1 expression." (PMID 30255595, 2018). "Taken together, these data indicated that overexpression of miR-128 inhibits BMI-1 expression and reduces CSC-related characteristics in PTX-resistant lung cancer stem cells." (PMID 29299167, 2017). "In conclusion, our results revealed that miR-128 induces apoptosis of paclitaxel-resistant lung cancer cells and decreases MUC1 and stemness-related protein BMI-1 levels." (PMID 29299167, 2017). "BMI-1 has been shown to be involved in EMT in cancer cells, such as endometrial cancer, oral cancer, lung cancer and nasopharyngeal cancer." (PMID 26840020, 2016). "Immunohistochemical analyses of 187 early-stage lung cancer tumor specimens revealed a statistically significant co-expression of RRM1 and Bmi1." (PMID 24614341, 2014). "We describe the RRM1, RNF2, and Bmi1 interaction and co-localization, the mechanisms by which RNF2 and Bmi1 regulate RRM1 levels and cellular response to gemcitabine, and in situ protein levels in tumor specimens derived from patients with lung cancer." (PMID 24614341, 2014). "With the exception of OCT4, other markers Bmi1, CD133, CD44, Sox2, Nanog and Msi2 mRNA and protein were abundantly expressed in lung cancer." (PMID 23683495, 2013). "The expressions of Oct4, Bmi1, and ALDH1 are involved in maintaining cancer stem-like cells in lung cancer." (PMID 22662215, 2012). "We analyzed the expression profile of putative surface (CD34, CD44, CD133) and nuclear markers (BMI1, OCT4) of stem cells in 10 lung cancer cell lines using flow cytometry." (PMID 21124918, 2010). "The expression profiles of five stem cell markers (CD34, CD44, CD133, BMI1 and OCT4) were screened by flow cytometry in 10 lung cancer cell lines." (PMID 21124918, 2010). "To explore further lung CSC markers, we have screened the expression profile of CD34, CD44, CD133, BMI1 and OCT4 in 10 lung cancer cell lines by flow cytometry." (PMID 21124918, 2010). "We then investigated the clinical significance of BMI1 and MCL1 in lung cancer patients." (PMID 35794816, 2022). "Finally, to confirm the in vitro and in vivo findings, we analyzed the expression of ZEB1, BMI1, and ALDH1A1 by immunohistochemistry in lung cancer specimens obtained from 20 NSCLC patients before treatment and after relapse during treatment with gefitinib." (PMID 33764690, 2021). "Finally, the lung cancer specimens from patients with acquired resistance to EGFR‐TKI showed increased expression of ZEB1, BMI1, and ALDH1A, than in specimens before treatment." (PMID 33764690, 2021).
lung cancer (continued). "To further investigate the downstream mechanisms of LncRNA NR2F2‐AS in lung cancer cells, we also transfect A549 and SPC‐A‐1 cells with si‐BMI1 to compare the effects of si‐LncRNA NR2F2‐AS, miR‐320b mimic and si‐BMI1 among cell proliferation, invasion and apoptosis." (PMID 30592135, 2019). "Our results supported the hypothesis that miR-128 treatment is a potential therapeutic strategy for paclitaxel-resistant lung cancer by targeting MUC1-C and BMI-1." (PMID 29299167, 2017). "In lung cancer, however, the role of BMI1 has not been fully characterized." (PMID 35794816, 2022). "Furthermore, CBX4 has been shown to promote proliferation and metastasis by regulating the BMI-1 pathway, thus suggesting that CBX4 might be a potential therapeutic target in lung cancer." (PMID 34046352, 2021). "However, to the best of our knowledge, no study has examined the expression of both ZEB1 and BMI1 in lung cancer specimens from patients with acquired resistance to EGFR‐TKI." (PMID 33764690, 2021). "Furthermore, overexpression of self-renewal genes such as Bmi1, ALDH1, and Oct-4 indicates that lung cancer cells may acquire stem cell-like properties from MSCs by fusion." (PMID 24516569, 2014). "In this study, we applied RT-PCR to examine the differential expression of Bmi1, CD133, CD44, Sox2, Nanog, OCT4 and Msi2 mRNA in bronchoscopic biopsy specimens from lung cancer and non-cancer patients." (PMID 23683495, 2013). "In this study, our results showed that the mRNA levels of Bmi1, CD44 and CD133 were not significantly different between lung cancer and non-malignant lung tissues." (PMID 23683495, 2013). "However, the mRNA relative levels of Bmi1, CD133 and CD44 by RT-PCR were not significantly different between lung cancer and non-malignant lung tissues analyzed by Mann–Whitney U test, nor were the expression rates of CD44 and Msi2." (PMID 23683495, 2013).
gastric cancer (55 papers, 2010 to 2025). A primary or metastatic malignant neoplasm involving the stomach. "More recently, we identified a positive correlation between GLUT1 expression and Bmi-1 expression in gastric cancer, and a higher expression of Bmi-1 was associated with a higher degree of tumor malignancy (data not published yet)." (PMID 35415241, 2022). "Through clinical specimen analysis, overexpression of USP22 and BMI1 was associated with gastric cancer progression and treatment failure." (PMID 35935969, 2022). "In our study, we found that miR-128 and Bmi-1 can be used as diagnostic markers for gastric cancer, and high levels of miR-128, as well as low levels of Bmi-1, were significantly associated with long overall survival of gastric cancer patients." (PMID 28424413, 2017). "Our previous studies have found that Bmi-1 expression in gastric cancer is associated with lymph node metastasis and clinical stage and is an independent prognostic factor in patients with gastric cancer." (PMID 27644439, 2016). "High levels of Bmi-1 in gastric cancer patients are significantly associated with better overall survival (P = 0.024) based on the Kaplan-Meier survival analysis." (PMID 26894855, 2016). "In accordance with these findings, several other studies have found that Bmi-1 is upregulated in gastric cancer and is associated with decreased survival rates in patients." (PMID 25295122, 2014). "Decreased Mel-18 and increased Bmi-1 mRNA expression was associated with the carcinogenesis and progression of gastric cancer." (PMID 21059209, 2010). "In addition, high BMI1 protein expression in primary tumors is associated with decreased survival of patients with lymphoma and in patients with liver or gastric cancers." (PMID 28445986, 2017). "It suggests that Bmi-1 may play a crucial role and act as an oncogene in gastric cancer, and associated with the carcinogenesis, progression, and metastasis of gastric cancer." (PMID 21059209, 2010). "It provides more convincing in vivo data to suggest that Mel-18 may play a crucial opposite role to Bmi-1 and act as a tumor suppressor in gastric cancer, and associated with the carcinogenesis, progression, and metastasis of gastric cancer." (PMID 21059209, 2010). "In gastric cancer, BMI1 upregulates miR-27a and miR-155 to target RKIP, thereby promoting metastasis and chemoresistance." (PMID 40623983, 2025). "In gastric cancer, the microRNAs miR-498 and miR-218 inhibited Bmi-1 function, as well as EMT and Akt signaling." (PMID 36726797, 2023). "Some previous studies by others have also indicated that Bmi-1 expression is increased in GAC and that the overexpression of Bmi-1 leads to enhancement in the proliferation, invasion, and metastasis of gastric cancer." (PMID 35415241, 2022). "More recently, we noticed that there was a significant correlation between GLUT1 expression and Bmi-1 expression in gastric cancer (unpublished data)." (PMID 35415241, 2022). "We also identified a positive correlation between a higher expression of Bmi-1 and more advanced clinical stages, according to the clinicopathologic classifications of patients with gastric cancer." (PMID 35415241, 2022). "A number of previous studies have demonstrated that Bmi-1 is involved in multiple cellular processes to promote the proliferation, invasion, and metastasis of gastric cancer; and its expression is positively correlated with the malignancy of gastric cancer." (PMID 35415241, 2022). "The expressions of USP22 and BMI1 are closely related in various cancer tissues, such as liver cancer, colorectal cancer, and gastric cancer." (PMID 35935969, 2022). "USP22 maintains stemness of CSC and promotes gastric cancer development through stabilizing the BMI1 protein." (PMID 34753387, 2021). "Increased levels of BMI-1 activated the stemness state in gastric cancer cells, induced by overexpression of SALL4." (PMID 32819319, 2020).